SFRP4 (secreted frizzled related protein 4)
Description:
Soluble frizzled-related proteins (sFRPS) function as modulators of Wnt signaling through direct interaction with Wnts. They have a role in regulating cell growth and differentiation in specific cell types (By similarity). SFRP4 plays a role in bone morphogenesis. May also act as a regulator of adult uterine morphology and function. May also increase apoptosis during ovulation possibly through modulation of FZ1/FZ4/WNT4 signaling (By similarity). Has phosphaturic effects by specifically inhibiting sodium-dependent phosphate uptake.
Synonyms: sFRP-4; FrpHE; FRP-4; FRZB-2; PYL
Tractability: Antibody: UniProt places it where antibodies can reach, with high confidence; UniProt predicts a signal peptide or a membrane-spanning region; its Gene Ontology location is reachable by antibodies, with medium confidence.
Gene: Protein-coding gene on chromosome 7 (37,905,932 to 38,025,695, reverse strand). Ensembl gene ENSG00000106483.
Subcellular location: Secreted
Gene Ontology:
Molecular function: protein binding; Wnt-protein binding
Biological process: bone morphogenesis; negative regulation of canonical Wnt signaling pathway; negative regulation of cell population proliferation; negative regulation of sodium-dependent phosphate transport; negative regulation of transcription by RNA polymerase II; phosphate ion homeostasis; positive regulation of apoptotic process; positive regulation of canonical Wnt signaling pathway; positive regulation of epidermal cell differentiation; positive regulation of gene expression; positive regulation of keratinocyte apoptotic process; positive regulation of receptor internalization; canonical Wnt signaling pathway; negative regulation of non-canonical Wnt signaling pathway; negative regulation of Wnt signaling pathway; non-canonical Wnt signaling pathway; regulation of BMP signaling pathway; response to hormone; animal organ morphogenesis; skeletal system development
Cellular component: cell surface; cytoplasm; extracellular region; nucleus
Genetic constraint (gnomAD): Loss-of-function variants: 19 observed, 32.53 expected, observed/expected ratio (o/e) 0.58, 90% interval 0.41 to 0.86. The upper end of that interval is the gene's LOEUF score, 0.86, which puts it in group 3 of 6, group 1 being the genes least tolerant of losing a copy. Missense variants: 445 observed, 450.6 expected, observed/expected ratio (o/e) 0.99, 90% interval 0.91 to 1.07. Synonymous variants: 167 observed, 172.44 expected, observed/expected ratio (o/e) 0.97, 90% interval 0.85 to 1.1.
Homologues: Orthologues: chimpanzee SFRP4 (99% identical), macaque SFRP4 (99% identical), pig SFRP4 (96% identical), rabbit SFRP4 (96% identical), dog SFRP4 (95% identical), mouse Sfrp4 (93% identical), rat Sfrp4 (93% identical), guinea pig SFRP4 (92% identical), tropical clawed frog sfrp4 (67% identical), Drosophila melanogaster fz2 (25% identical), Caenorhabditis elegans cfz-2 (25% identical), Drosophila melanogaster fz3 (19% identical), and 1 more. Paralogues in human: FRZB (46% identical), FZD8 (27% identical), FZD2 (27% identical), FZD1 (27% identical), FZD9 (27% identical), FZD5 (27% identical), FZD7 (27% identical), FZD3 (26% identical), FZD10 (25% identical), FZD4 (24% identical), FZD6 (22% identical), SMO (18% identical), and 3 more.
Diseases named in the same sentence as SFRP4 in open-access papers:
SFRP4 is named in the same sentence as 174 diseases in open-access papers, as found by Europe PMC text mining. Sharing a sentence is not in itself a finding about the gene and the disease. The quoted sentences say what the papers report.
ovarian carcinoma (23 papers, 2012 to 2025). A malignant neoplasm originating from the surface ovarian epithelium. "Decreased expression of SFRP4, a secreted Wnt inhibitor, is linked to unfavorable prognosis in ovarian cancer." (PMID 40710326, 2025). "Wnt signaling can be competitively inhibited by secreted frizzled-related protein 4 (SFRP4), the loss of which has been associated with poor outcomes in ovarian cancer patients and decreased responsiveness of ovarian cancer cells to cisplatin in vitro." (PMID 26343197, 2015). "This study aimed to evaluate trefoil factor 3 (TFF3), secreted frizzled-related protein 4 (sFRP4), reactive oxygen species modulator 1 (Romo1) and nuclear factor kappa B (NF-κB) as diagnostic and prognostic markers of endometrial cancer (EC) and ovarian cancer (OC)." (PMID 35461390, 2022). "Its loss was noticed in aggressive ovarian cancer types and recombinant SFRP4 (rSFRP4) treatment of serous ovarian cancer cells that result in the inactivation of the Wnt/β-catenin pathway, mesenchymal-to-epithelial transition, and decreasing ability to migrate." (PMID 35095892, 2021). "Low SFRP4 expression is associated with an unfavorable prognosis in prostate and ovarian cancer." (PMID 29037197, 2017). "The loss of SFRP4 expression in our study of ovarian oncogenesis supports the results found in other cancers and suggests a tumor suppressor function for SFRP4 also in ovarian cancers." (PMID 22363760, 2012). "Also SFRP4 confers chemo-sensitization and improve chemotherapeutic efficacy, which possesses both diagnostic and therapeutic potential in epithelial ovarian cancer." (PMID 33987033, 2021). "It was shown that SFRP4 can predict the survival time of patients with gastric cancer and ovarian cancer and is an important immune-related factor." (PMID 39729237, 2025). "In ovarian cancer, miR-181a promotes the Wnt/β-catenin signaling pathway by targeting and inhibiting SFRP4, a Wnt signaling pathway inhibitor, hence augmenting ovarian cancer stem cell (OCSC) traits and generating resistance to platinum-based chemotherapy." (PMID 40710326, 2025). "Downregulation of sFRP4 expression in breast, prostate, and ovary cancer stem cells can be attributed to aberrant promoter hypermethylation together with histone modification." (PMID 38993819, 2024). "SFRP4 inhibits Wnt signaling pathway and decreases transcription of Wnt target genes, Axin2, CyclinD1 and Myc, reducing migration ability of ovarian cancer cells by increasing the ability to adhere to collagen and fibronectin." (PMID 33987033, 2021). "For example, the addition of recombinant protein secreted frizzled-related protein 4 (sFRP4) has been positively associated with response to cisplatin and doxorubicin in cancer stem cells (CD133+/CD44+) isolated from A2780 ovarian cancer cell line." (PMID 30894224, 2019). "In ovarian cancer, modulation of a single upstream gate-keeper of Wnt signaling, secreted frizzled related protein 4 (SFRP4), which functions as a tumor suppressor, can activate Wnt signaling and promote EMT." (PMID 29986466, 2018). "Conversely, we were able to demonstrate that silencing of sFRP4 in A2780 ovarian cancer cells resulted in upregulation of β-catenin expression." (PMID 25714610, 2015). "Expression of secreted frizzled related protein 4 (SFRP4), an extracellular modulator of the Wnt signalling pathway, is progressively lost in more aggressive ovarian cancer phenotypes." (PMID 23326605, 2013). "We have previously shown that one of these gatekeepers, SFRP4, is secreted into the blood stream and progressively lost in more aggressive ovarian cancer phenotypes, such as Type II cancers." (PMID 23326605, 2013). "Down regulation of SFRP1, SFRP4 and 5 are reported in aggressive breast cancer, ovarian cancer and gastric cancer respectively." (PMID 23825088, 2013).
ovarian carcinoma (continued). "We report for the first time that re-expression of SFRP4 in an epithelial ovarian cancer cell line inhibits Wnt signalling, increases adhesion, inhibits cell migration and inhibits EMT." (PMID 23326605, 2013). "SFRP4 expression was then measured at the protein level in various healthy and ovarian cancer cell lines by Western-blot." (PMID 22363760, 2012). "In this study we investigated the effects of over-expressing or silencing of sFRP4 in ovarian cancer lines with different chemosensitivity in an in vitro model." (PMID 23039795, 2012). "Apart from confirming an inhibitory effect of SFRP4 in all histotypes of ovarian cancer, this study also demonstrated for the first time that the secreted levels of SFRP4 can indeed be detected in human blood and can therefore be used diagnostically." (PMID 22363760, 2012). "SFRP4 was expressed on the protein level in all histotypes of ovarian cancer but was decreased from borderline tumors to cancers and with loss of cellular differentiation." (PMID 22363760, 2012). "Our results support a role for SFRP4 as a tumor suppressor gene in ovarian cancers via inhibition of the Wnt signaling pathway." (PMID 22363760, 2012). "This conjoint finding of highest SFRP4 expression in tubal epithelium and lowest in Type II ovarian cancers fits optimally to the proposed model that Type II cancers derive rather from the tubal epithelium and not the ovarian surface epithelium." (PMID 22363760, 2012). "We describe how the short active peptide derivatives of sFRP4 could be the latest breakthrough in peptide-based drug compounds for the treatment of highly malignant and aggressive ovarian cancer." (PMID 36831617, 2023). "Moreover they postulated a role for SFRP4 as a tumor suppressor gene in ovarian cancers via inhibition of the Wnt signaling pathway." (PMID 25127546, 2014). "This raises the possibility that SFRP4 may be used both diagnostically and therapeutically in epithelial ovarian cancer." (PMID 23326605, 2013). "On the other hand the lowest SFRP4 levels were found in Type II ovarian cancers (advanced stage/undifferentiated serous cancers and carcinosarcoma), which are increasingly thought to be a distinct molecular entity from the less aggressive Type I ovarian cancers." (PMID 22363760, 2012). "This study indicates a role for sFRP4 as a predictive marker of chemosensitivity in ovarian cancer and suggests that this pathway may be worth exploiting for novel therapies." (PMID 23039795, 2012). "In contrast to previous literature on endometrioid endometrial cancers, SFRP4 expression was similarly distributed in all histological subtypes of ovarian cancer, although in plasma, patients with endometrioid ovarian cancers showed a trend towards higher SFRP4 expression (N.S. p = 0.23)." (PMID 22363760, 2012). "Using ascites at two consecutive time points from two cancer patients with supposedly different aggressiveness (Pt 1 mixed ovarian cancer G1, Pt 2 serous peritoneal cancer G3), these experiments showed a reduction of SFRP4 protein expression during progressive chemoresistant disease." (PMID 22363760, 2012). "Since SFRP4 expression has been shown to be lost in a large majority of ovarian cancer patients, this raises the possibility that modulation of Wnt signalling through SFRP4 or other upstream Wnt pathway members may represent a new avenue for targeted therapy in ovarian cancer." (PMID 23326605, 2013). "We did not examine our ovarian cancer cell lines on whether low sFRP4 expression was associated with hypermethylation of the sFRP4 gene itself, and this would be useful to know." (PMID 23039795, 2012). "SFRP4 was highly expressed in primary tubal cultures when compared to the normal ovarian surface epithelial cell line HOSE6-3 and was particularly high in the patient with the BRCA mutation (Tube 1) as compared to the patient with positive family history of breast/ovarian cancer (Tube 2)." (PMID 22363760, 2012).
ovarian carcinoma (continued). "Thus, the results from this study indicate a role for sFRP4 as a predictive marker for ovarian cancer cell chemosensitivity, and suggest that targeting the sFRP4 mediated pathway may be worth pursuing as a novel therapeutic target." (PMID 23039795, 2012). "Previous studies reported that SFRP4 modulated EMT, cell migration, and WNT signaling in ovarian cancer cells and promoted apoptosis in glioblastoma cells." (PMID 38686196, 2024). "Subsequently, the remaining prognostic biomarkers from other cancer types were also assessed by OSov, which demonstrated that these genes (SFRP4, NUAK1, MFAP2, PLIN1 and EFNB2) exhibited good performance in predicting ovarian cancer patient outcome." (PMID 35053021, 2021). "We previously performed transcription profiling in ovarian cancer specimens compared to normal ovarian controls which revealed aberrant expression of SFRP1 and SFRP4 in ovarian cancers." (PMID 22363760, 2012). "Could the functional peptides of sFRP4, in targeting ovarian cancers and their aggressive CSC population, evolve into a promising peptide drug panel for treating highly malignant and drug-resistant ovarian cancer?" (PMID 36831617, 2023).
diabetes (19 papers, 2013 to 2024). "SFRP4 is secreted in the systemic circulation many years before the onset of diabetes and causes severe β-cell dysfunction, impaired glucose metabolism, and insulin resistance." (PMID 37943820, 2023). "Another candidate region is in chromosome 7 and is upstream of SFRP4, which encodes a protein associated with diabetes and Pyle’s disease." (PMID 34032215, 2021). "SFRP4 influences a wide scope of genes of Wnt signaling and several genes variants from the pathway have been linked to the pathogenesis of Type 2 diabetes mellitus." (PMID 29069795, 2017). "Secreted frizzled-related protein 4 (SFRP4) is found to cause five times more risk of diabetes when expressed above average levels." (PMID 25019556, 2014). "Higher SFRP4 concentrations were associated with type 2 diabetes, metabolic syndrome, and severity of diabetes." (PMID 25408147, 2014). "SFRP4 causes reduction in insulin secretion and it is over- expressed in type 2 diabetes mellitus so the inhibition of SFRP4 results in the proper secretion of insulin leading to control of diabetes type 2." (PMID 25019556, 2014). "SFRP4 correlates positively with the stage of prediabetes, suggesting that it may be an early biomarker to predict the risk of developing diabetes in people with high serum concentrations of SFRP4, although further longitudinal studies are required." (PMID 38834984, 2024). "Furthermore, recent studies in patients with gestational diabetes demonstrated that increased SFRP4 levels in the first trimester of pregnancy were significantly associated with diabetes development and might be an important risk factor for this complication." (PMID 38834984, 2024). "In this sense, individuals with increased levels of SFRP4 in the blood are five times more likely to develop diabetes in the coming years." (PMID 38834984, 2024). "Impaired SFRP4 levels are involved in different pathologies, especially metabolic disorders such as obesity and diabetes." (PMID 38834984, 2024). "In this current study, the CADD approaches are used to identify promising phytochemical candidates for modulating SFRP4—a potential avenue for treating obesity-induced diabetes." (PMID 37943820, 2023). "The expression of SFRP4 is also connected with miR-30d, miR-146a, and miR-24, which are elevated in the serum of patients with diabetes." (PMID 35457182, 2022). "Multiple clinical studies proved that SFRP4 is involved in the occurrence and development of T2DM, as elevated serum SFRP4 puts patients at three-folds higher risk of developing diabetes." (PMID 34489867, 2021). "Adipocyte hypertrophy contributes to insulin resistance, and SFRP4 is overexpressed in type 2 diabetes mellitus." (PMID 32657640, 2020). "In fact, platelet-derived miR-103b is able to downregulate SFRP4, whose expression levels are significantly increased in pancreatic islets and in the blood of patients with prediabetes or overt diabetes." (PMID 29387042, 2018). "SFRP4 is an adipokine, and serum SFRP4 levels have been shown to be elevated in patients with different types of diabetes, even a few years before clinical diagnosis of diabetes." (PMID 29037197, 2017). "Bone fragility under oxidative stress by diabetes and aging is partly related to the suppression of the Wnt signal through upregulated sFRP4." (PMID 27117872, 2016). "This discrepancy underlines the need for standardized assays for the necessary studies to further evaluate the role of SFRP4 in diabetes." (PMID 25408147, 2014). "SFRP4 has been shown to regulate insulin exocytosis and is overexpressed in type 2 diabetes mellitus." (PMID 25408147, 2014). "Comparison of SFRP4 concentrations between strata of categorical variables showed that SFRP4 levels were higher in patients with metabolic syndrome, insulin therapy, diabetes and a history of myocardial infarction or PCI." (PMID 25408147, 2014).
diabetes (continued). "The findings suggest the possible treatment of diabetes mellitus type 2 by inhibiting the SFRP4 using the inhibitors cyclothiazide, clopamide and perindopril." (PMID 25019556, 2014). "Further research is necessary to elucidate the relevance of SFRP4 levels in healthy people and patients with cardiovascular disease and its prognostic value for diabetes and cancer." (PMID 25408147, 2014). "This work is carried out to find potential inhibitors of SFRP4 protein to control diabetes mellitus type 2." (PMID 25019556, 2014). "Individuals having increased levels of SFRP4 in the blood are five times more likely to develop diabetes in the coming years." (PMID 25019556, 2014). "SFRP4 is an inflammatory mediator and a potential target for preserving β-cell function and acts as an early biomarker for the treatment of obesity-induced diabetes (diabesity)." (PMID 37943820, 2023). "The overexpression of SFRP4 is positively and indirectly related to the development of diabetes." (PMID 35457182, 2022). "There is a growing body of literature that recognizes the importance of SFRP4 in diabetes." (PMID 35290144, 2022). "Diabetes could induce the expression of Sfrp1 and Sfrp4, but FoxO1 knockout slightly reduced Sfrp1 level." (PMID 33609082, 2021). "Another interesting mechanism linking platelets and diabetes involves miR-103b, a platelet-derived biomarker proposed for the early diagnosis of type 2 DM, and the secreted frizzled-related protein-4 (SFRP4), a potential biomarker of early β cell dysfunction and diabetes." (PMID 29387042, 2018). "A recent cross-sectional clinical study of serum sFRP4 in humans with type 2 diabetes mellitus compared to pre-diabetes and normal glucose tolerance subjects revealed higher sFRP4 in subjects with diabetes and a positive correlation between sFPR4 and age, insulin levels, HbA1c and triglycerides." (PMID 27685706, 2016). "A trigger for the increased expression of SFRP4 in diabetes can be methylglyoxal." (PMID 25408147, 2014). "Interestingly, in two small cohorts SFRP4 was elevated several years before clinical diagnosis of diabetes, assuming the possibility of SFRP4 as an early diabetes marker." (PMID 25408147, 2014). "In this study by using the in-silico approach we have found some potential inhibitors against SFRP4, which in the future may pave the way for diabetes mellitus cures by decreasing the expression of SFRP4 and increasing insulin production." (PMID 25019556, 2014). "As a member of the SFRPs family, since the discovery of SFRP4, studies on its role in diabetes, obesity, and lipid metabolism have continuously revealed its important roles, providing a new direction and strategy for the treatment of diabetes and lipid metabolism-related diseases." (PMID 37143778, 2023). "Another group discovered that miR-103a and miR-103b negatively regulate the expression of SFRP4 by regulating the 3’-noncoding region, suggesting that their mutual changes provide high sensitivity and specificity for the identification of patients with pre-diabetes." (PMID 34489867, 2021). "Therefore, identifying the role of SFRP4 in obesity and its molecular mechanism of how it leads to obesity and eventually to diabetes may help to design new therapeutic approaches to treat obese patients suffering from diabetes." (PMID 35290144, 2022). "The molecular mechanisms of SFRP1, SFRP4, and SFRP5 may have a direct or indirect effect on the development of diabetes." (PMID 35457182, 2022).